SLC5A7 (solute carrier family 5 member 7)
Description:
High-affinity Na(+)-coupled choline transmembrane symporter. Functions as an electrogenic, voltage-dependent transporter with variable charge/choline stoichiometry. Choline uptake and choline-induced current is also Cl(-)-dependent where Cl(-) is likely a regulatory ion rather than cotransported ion. Plays a critical role in acetylcholine (ACh) synthesis by taking up the substrate choline from the synaptic cleft into the presynaptic nerve terminals after neurotransmitter release. SLC5A7/CHT1-mediated choline high-affinity transport in cholinergic neurons is the rate-limiting step for production of ACh, thereby facilitating communication by subsequent action potentials. Localized predominantly in presynaptic terminal intracellular organelles, and translocated to the plasma membrane in active form in response to neuronal activity.
Synonyms: hCHT1; CHT; CHT1; hCHT; CMS20; DHMNVP; HMN7A; HMND7
Tractability: Small molecule: a structure with a bound ligand is known; a high-quality ligand is known; it belongs to a druggable protein family. Antibody: UniProt places it where antibodies can reach, with high confidence; its Gene Ontology location is reachable by antibodies, with high confidence; UniProt predicts a signal peptide or a membrane-spanning region. PROTAC: a small molecule that binds it is known.
Target class: SLC superfamily of solute carriers; SLC05 family of sodium-dependent glucose transporters; Electrochemical transporter; Transporter
Chemical probes: ML352
Gene: Protein-coding gene on chromosome 2 (107,986,523 to 108,013,994, forward strand). Ensembl gene ENSG00000115665.
Subcellular location: Presynaptic cell membrane; Cell projection, axon; Early endosome membrane; Cytoplasmic vesicle, secretory vesicle, synaptic vesicle membrane
Subcellular location (Human Protein Atlas): Cell Junctions; Intermediate filaments; Nuclear bodies
Pathways (Reactome):
Disease: Defective SLC5A7 in the neurotransmitter release cycle causes distal hereditary motor neuronopathy 7A (HMN7A); Defective transport by SLC5A7 causes distal hereditary motor neuronopathy 7A (HMN7A)
Neuronal System: Acetylcholine Neurotransmitter Release Cycle
Transport of small molecules: SLC-mediated bile acid transport
Gene Ontology:
Molecular function: choline transmembrane transporter activity; choline:sodium symporter activity; choline binding; transmembrane transporter activity
Biological process: acetylcholine biosynthetic process; choline transport; bile acid and bile salt transport; neuromuscular synaptic transmission; neurotransmitter transport; synaptic transmission, cholinergic; transmembrane transport
Cellular component: early endosome membrane; membrane; neuromuscular junction; plasma membrane; presynaptic membrane; synaptic vesicle membrane; axon; dendrite; perikaryon; synapse; neuronal cell body; presynapse
Genetic constraint (gnomAD): Loss-of-function variants: 16 observed, 52.63 expected, observed/expected ratio (o/e) 0.3, 90% interval 0.2 to 0.46. The upper end of that interval is the gene's LOEUF score, 0.46, which puts it in group 2 of 6, group 1 being the genes least tolerant of losing a copy. Missense variants: 481 observed, 697.93 expected, observed/expected ratio (o/e) 0.69, 90% interval 0.64 to 0.74. Synonymous variants: 253 observed, 262.68 expected, observed/expected ratio (o/e) 0.96, 90% interval 0.87 to 1.07.
Gene-disease validity (ClinGen):
ClinGen rates the evidence that SLC5A7 causes each of these diseases.
neuronopathy, distal hereditary motor, type 7A (autosomal dominant): Moderate.
Homologues: Orthologues: chimpanzee SLC5A7 (99% identical), macaque SLC5A7 (99% identical), rabbit SLC5A7 (94% identical), rat Slc5a7 (93% identical), mouse Slc5a7 (93% identical), dog SLC5A7 (93% identical), guinea pig SLC5A7 (91% identical), pig SLC5A7 (91% identical), tropical clawed frog slc5a7 (81% identical), zebrafish slc5a7a (75% identical), zebrafish SLC5A7 (58% identical), Drosophila melanogaster rumpel (17% identical), and 9 more. Paralogues in human: SLC5A8 (19% identical), SLC5A12 (19% identical), SLC5A2 (19% identical), SLC5A5 (19% identical), SLC5A6 (19% identical), SLC5A10 (18% identical), SLC5A1 (17% identical), SLC5A11 (17% identical), SLC5A9 (17% identical), SLC5A4 (17% identical), SLC5A3 (16% identical).
Diseases named in the same sentence as SLC5A7 in open-access papers:
SLC5A7 is named in the same sentence as 110 diseases in open-access papers, as found by Europe PMC text mining. Sharing a sentence is not in itself a finding about the gene and the disease. The quoted sentences say what the papers report.
congenital myasthenic syndrome (8 papers, 2018 to 2024). Congenital myasthenic syndrome (CMS) is a group of genetic disorders of impaired neuromuscular transmission at the motor endplate characterized by fatigable muscle weakness. "Human mutations in SLC5A7 are associated with congenital myasthenic syndrome, which is characterized by muscle weakness and fatigue." (PMID 34061829, 2021). "This clinical presentation is then compared with the recently described phenotype arising from recessively acting CHT mutations, consisting of a spectrum of congenital myasthenic syndrome (CMS) disorders, associated with biallelic SLC5A7 mutations." (PMID 29582019, 2018). "Mutations in the SLC5A7 gene cause congenital myasthenia, a rare genetic disorder." (PMID 38886633, 2024). "The identification of a variant in SLC5A7 in a patient with congenital myasthenic syndrome (CMS) indicated that the patient had the very rare and severe CMS Type 20, characterised by life-threatening respiratory episodes, which benefit from cholinesterase inhibitors, and potentially, salbutamol." (PMID 37946251, 2023). "This study aims to explore the clinical phenotype and genetic traits of a patient with congenital myasthenic syndrome due to SLC5A7 gene variation and those of their family members." (PMID 38886633, 2024).
colorectal cancer (5 papers, 2015 to 2025). A primary or metastatic malignant neoplasm that affects the colon or rectum. "In colorectal cancer, promoter methylation and the resultant low expression of SLC5A7 are poor prognostic factors as our results." (PMID 38745021, 2024). "SLC5A7 (solute carrier family 5 member 7), also known as choline transporter 1 (CHT1), is downregulated in colorectal cancer (CRC) and functions as a tumor suppressor." (PMID 35858918, 2022).
neuropathies (4 papers, 2018 to 2025). "CEP72 rs924607 is associated with neuropathies, and ADME analyses show associations between neuropathies and ABCC1 rs3784867, and SLC5A7 rs1013940." (PMID 34948113, 2021). "No signs of neuropathy have been reported in autosomal recessive SLC5A7 CMS, although it is possible that these features might develop with time." (PMID 29582019, 2018).
Alzheimer disease (3 papers, 2018 to 2025). A progressive, neurodegenerative disease characterized by loss of function and death of nerve cells in several areas of the brain leading to loss of cognitive function such as memory and language. "Mutations in SLC5A7 have been shown to underlie the dysfunction of cholinergic neurotransmission, which might lead to pathogenesis, including Alzheimer’s disease (AD), myasthenia, cardiovascular disorders, depression, and attention-deficit/hyperactivity disorder (ADHD)." (PMID 35858918, 2022).
breast carcinoma (3 papers, 2016 to 2022). "SLC5A7 had elevated mRNA expression in breast cancer cells compared with mammary epithelial cells." (PMID 28427185, 2017).
autosomal dominant dHMN (2 papers, 2018 to 2024). "Mutations in the SLC5A7 gene have been linked to only two clinical phenotypes: VIIa, an autosomal dominant distal hereditary motor neuropathy, and CMS20, an autosomal recessive disorder." (PMID 38886633, 2024).
Cognitive impairment (2 papers, 2019 to 2026). Abnormal cognition is characterized by deficits in thinking, reasoning, or remembering. "Mild to severe cognitive impairment has been reported in patients carrying mutations in the SLC5A7 gene, DPAGT1 gene, SNAP25 gene, COL13A1 gene, MYO9A gene, MUNC13–1 gene, and in SCN4A-related CMS." (PMID 30808424, 2019).
Hypertension (2 papers, 2020 to 2021). The presence of chronic increased pressure in the systemic arterial system. "Certain genes involved in the pathogenesis of hypertension—Alb, Chrm2, Xirp1, Kcnq1, Slc5a7, Kcnh1, Ache, Crlf1 and Galr2— should also be studied." (PMID 34603037, 2021).
bipolar disorder (1 paper, 2018). A disorder of the brain that causes unusual shifts in mood, energy, activity levels and the ability to carry out day-to-day tasks. "The variants are in the Npas2, Cp, Polr3c, Smarca4, Trpv1, and Slc5a7 genes, and many of these genes’ products are in pathways implicated in human bipolar disorders." (PMID 29768498, 2018).
colon cancer (1 paper, 2022). "Furthermore, inverse correlations between SLC5A7 expression and SLC5A7 methylation levels were observed in malignant colon cancer tissues." (PMID 35858918, 2022).
distal hereditary motor neuropathy type 7 (1 paper, 2025). "A heterozygous variant in the Solute carrier family-5 member-7 (SLC5A7) gene, associated with autosomal dominant distal hereditary motor neuropathy type 7 (dHMN7)." (PMID 41509941, 2025).
hepatocellular carcinoma (1 paper, 2024). A malignant tumor that arises from hepatocytes.
lung adenocarcinoma (1 paper, 2022). A carcinoma that arises from the lung and is characterized by the presence of malignant glandular epithelial cells. "Yang and colleagues revealed that SLC5A7 was hypermethylated and downregulated in lung adenocarcinoma (LUAD), but not in lung squamous cell carcinoma (LUSC)." (PMID 35858918, 2022).
psoriasis (1 paper, 2025). An autoimmune condition characterized by red, well-delineated plaques with silvery scales that are usually on the extensor surfaces and scalp. "Among the top 10 downregulated and top 10 upregulated DEG, we identified several key genes related to psoriasis, including Krt25, Krt8, Muc16, Slc5a7, Reg3b." (PMID 39665264, 2025).
respiratory failure (1 paper, 2023). The significant impairment of gas exchange within the lungs resulting in hypoxia, hypercarbia, or both, to the extent that organ tissue perfusion is severely compromised. "Mice deficient for Slc5a7 dies in a few minutes after birth probably due to respiratory failure, and spinal motor neuron-specific rescue of Slc5a7 prolonged the knockout move and breath for ~24 h after birth." (PMID 36835142, 2023).
Vocal cord paralysis (1 paper, 2024). A loss of the ability to move the vocal folds. "However, vocal cord paralysis has also been reported in patients with distal HMN due to SLC5A7 mutation and SMA-LED2 due to BICD2 mutation." (PMID 39457418, 2024).
tumor (9 papers, 2020 to 2026). "Mechanistically, circFBXW4 acts as a sponge of miR‐338‐5p to upregulate SLC5A7 and inhibit tumor progression." (PMID 38461489, 2024). "DEG analyses revealed the genes contributing to RFS and related to SUVmax (PSG5, TFF3, SOX2, SLC5A5, and SLC5A7) and tumor size (HOXD10, IFNA1, and FER1L6)." (PMID 38745021, 2024). "The implementation of targeted SLC5A7 DNA demethylation reagents resulted in significant anti-tumor effects both in vitro and in vivo." (PMID 35858918, 2022). "Next, to examine the possible anti-tumor effect of the selective de-methylation of SLC5A7 in CRC, further in vitro and in vivo experiments were performed using dCas9-based sgSLC5A7-2- and sgSLC5A7-3-transfected CRC cells." (PMID 35858918, 2022). "In vivo and in vitro experiments also demonstrated that targeted demethylation of the SLC5A7 promoter can strongly inhibit tumor proliferation and progression, and these effects might be mediated by increased SLC5A7 expression." (PMID 35858918, 2022). "The tumor‐suppressive effects may be exerted through the circFBXW4/miR‐338‐5p/SLC5A7 axis." (PMID 38461489, 2024).
cancer (6 papers, 2017 to 2024). A tumor composed of atypical neoplastic, often pleomorphic cells that invade other tissues. "Kaplan-Meier survival curves show that higher expression of PEG3 and SLC5A7 is also associated with better clinical outcomes in several cancer types." (PMID 28427185, 2017). "Accordingly, DNA methylation plays an important role in regulating SLC5A7 expression in cancer tissues." (PMID 35858918, 2022). "Our results would provide solid evidence for understanding the mechanisms underlying SLC5A7 downregulation and its role in CRC, and a potential therapeutic strategy for CRC, even for other cancers." (PMID 35858918, 2022). "In contrast, lower expression of the downregulated genes (such as SCARA5, MYOM1, NKAPL, PEG3, USP2, SLC5A7 and HMGCLL1) in various cancers is associated with poor clinical outcomes in cancer." (PMID 28427185, 2017). "Collectively, DNA promoter methylation caused inactivation of SLC5A7 in CRC, and targeted demethylation of SLC5A7 might be a therapeutic target for CRC and other cancers." (PMID 35858918, 2022). "However, studies have focused on the role of SLC5A7 in cancer development, and its expression level varies among different types of tumors." (PMID 35858918, 2022). "We identified consistently upregulated genes (such as E2F1, EZH2, FOXM1, MYBL2, PLK1, TTK, AURKA/B and BUB1) and consistently downregulated genes (such as SCARA5, MYOM1, NKAPL, PEG3, USP2, SLC5A7 and HMGCLL1) across various cancers." (PMID 28427185, 2017). "In our previous study, SLC5A7 was downregulated in CRC, and its expression was correlated with prognosis, which is consistent with a previous study indicating a similar trend of SCL5A7 in several other cancer types." (PMID 35858918, 2022). "In cancer, especially in CRC, the roles and molecular mechanisms of the SLC5 superfamily, including SLC5A7, in tumorigenesis and progression are almost entirely unknown." (PMID 35858918, 2022).
SLC5A7 also shares sentences with these, for which no sentence is quoted: myopia (19 papers); Anxiety (4); infection (4); diabetes (3); Gaucher disease (3); motor neuron disease (3); neurological disorders (3); Obesity (3); retinal diseases (3); ischemia (2); lysosomal storage disease (2); osteoarthritis (2); pancreatitis (2); retinopathy (2); Stroke (2); acid lipase deficiency (1); acute myocardial infarction (1); adenocarcinoma (1); age-related hearing loss (1); amyloid (1); amyotrophic lateral sclerosis (1); arrhythmogenic right ventricular cardiomyopathy (1); Astigmatism (1); astrocytoma (1); Atrophy (1); attention deficit-hyperactivity disorder (1); autism (1); autism spectrum disorder (1); autoimmune disease (1); autoimmune thyroiditis (1).
A further 62 diseases each share a sentence with SLC5A7 in 1 paper.